GJA1 (gap junction protein alpha 1)
Diseases named in the same sentence as GJA1 in open-access papers (continued):
Sharing a sentence is not in itself a finding about the gene and the disease.
Right ventricular cardiomyopathy (1 paper, 2025). Right ventricular dysfunction (global or regional) with functional and morphological right ventricular abnormalities, with or without left ventricular disease. "Many of the pathway genes recovered by post-flight period 82; however, some genes, such as GJA1 in the arrhythmogenic right ventricular cardiomyopathy pathways, did not recover after spaceflight in dendritic and B cells." (PMID 41009942, 2025).
situs inversus (1 paper, 2022). A congenital condition in which there is complete right-to-left reversal of the position of the major thoracic and abdominal organs (that is, they are arranged in a mirror image of the normal positioning). "Furthermore, we detected candidate variants in GJA1 and ACVR2B possibly associated with situs inversus." (PMID 35547246, 2022).
Spasticity (1 paper, 2013). A motor disorder characterized by a velocity-dependent increase in tonic stretch reflexes with increased muscle tone, exaggerated (hyperexcitable) tendon reflexes. "We expect that spasticity observed with ODDD is similarly related to non-functional Cx43/Cx47 GJs caused by mutations in the GJA1 gene; however, there are, to our knowledge, no records that address astrocyte-oligodendrocyte coupling with ODDD-linked Cx43 mutants." (PMID 24133447, 2013).
tumor (406 papers, 2004 to 2026). "Our study utilized several biological databases to evaluate the expression levels of GJA1 in pan-cancer, to analyze the diagnostic and prognostic significance of GJA1 in these tumor types, and to conduct cell experiments to further validate our findings." (PMID 38792963, 2024). "GJA1 (encoding Cx43) is a member of the connexin family that possesses both tumor-suppressive, and oncogenic functions." (PMID 35664298, 2022). "GJA1 is a gene encoding the protein connexin 43 (Cx43) that is a vital component of gap junctions and was disclosed to be of an important role in communication between tumor cells and surrounding immune cells like NK and dendritic cells (DC)." (PMID 35479936, 2022). "Among the genes encoding these proteins, encoding the gap junction alpha-1 (GJA1) protein has been identified as a tumor suppressor, and the expression of Cx43, produced by this gene, is negatively regulated in many human cancers." (PMID 35717615, 2022). "The Gja1 gene, which encodes a typical gap junction protein, connexin 43 (Cx43), has been identified as a tumor suppressor gene." (PMID 34630166, 2021). "Together, these results suggest that the expression of GJA1 is strongly associated with tumor subtype and is more variable in each subtype in comparison to morphologically normal tissue." (PMID 29495625, 2018). "Only one tumor with an extremely high number of total mutations (TCGA-AN-A046) was found to have both a GJA1 mutation and a slightly higher expression of the gene (2.76) compared to normal range (−1.01 to 2.20)." (PMID 29495625, 2018). "The Connexin 43 protein encoded by the GJA1 gene may regulate signaling between tumor cells and immune cells, affecting the infiltration and activity of immune cells, which in turn affects the prognosis of the patient." (PMID 38684858, 2024). "GJA1 encodes connexin-43, a gap junction protein that mediates tumor cell migration and invasion." (PMID 34711608, 2021). "Furthermore, the risk effect of GJA1 rs2071165 polymorphisms was more evident in the subgroups of female patients with GC, stratified by age, clinical stage, tumor size, and recurrence/metastasis." (PMID 34221012, 2021). "Furthermore, the risk effect of GJA1 rs2071165 was more evident in the subgroups of female patients with GC, stratified by age, clinical stage, tumor size, and recurrence/metastasis." (PMID 34221012, 2021). "Our data indicates that reduced Runx1 transcriptional activity downregulates Rspo3 oncogene expression, upregulates GJA1 tumor suppressor gene expression, significantly delays tumor cell migration and wanes cell number, in a susceptible manner to Foxp3's stalling activity." (PMID 26735887, 2016). "To address this issue, we calculated hazard ratio (HR) values for SEH1L, TUBA4A, TCF3, ZYX, and GJA1, both individually and in combination, using tumor data from The Cancer Genome Atlas (TCGA)." (PMID 41153808, 2025). "The results of our study highlighted a significant upregulation of GJA1 expression in six human tumor types: CHOL, ESCA, HNSC, KIRC, LIHC, and LUSC." (PMID 38792963, 2024). "The LMW PAHs increased the biomarkers of inflammation, decreased Gja1 expression, and increased Ereg expression, all consistent with tumor promotion." (PMID 39771097, 2024). "To further evaluate the effect of Cx43 on the tumour immune microenvironment, we utilised TIMER2.0 to investigate the correlation between GJA1 expression and infiltration level of CD8+ T cells in LUAD." (PMID 39592436, 2024). "Of the 24 tissue sections, proteins encoded by COL4A1, IGFBP3, and TIMP1 were slightly up-regulated in tumor tissues, while GHRL and GJA1 proteins were relatively down-regulated in tumor tissues than para-tumor tissues." (PMID 38273348, 2024). "Conversely, GJA1 expression was decreased in other eight tumor types, including BLCA, KICH, LUAD, PCPG, PRAD, READ, THCA, and UCEC." (PMID 38792963, 2024).
tumor (continued). "Examples of genes that are strongly correlated with NTRK2 in the astrocyte-like compartment include GJA1, TTHY1, GRIK1 and KCNN3; TTHY1 and GJA1 are known to have crucial roles in tumour microtube formation and connectivity in adult high-grade gliomas." (PMID 37914930, 2023). "Bioinformatic analysis revealed that the GJA1 expression was enhanced in HNSCC tumor tissues, and Kaplan–Meier survival data demonstrated that the higher GJA1 expression presented a worse OS rate in HNSCC patients." (PMID 35371339, 2022). "The upregulated GJA1 gene was further investigated as ectopic expression of its protein product connexin 43 (Cx43) in RMS cells was previously shown to elicit a tumor-suppressive phenotype similar to that of PANX1." (PMID 33564071, 2021). "Further, chi-squared (χ2) test showed that the high expression level of GJA1 was significantly correlated with keratinization, hormone use, tumor size, and FIGO stage." (PMID 33299882, 2020). "Using chi-squared (χ2) test, the high expression level of GJA1 was significantly correlated with keratinization (p = 0.045), hormone use (p = 0.019), tumor size (0.042), and FIGO stage (p = 0.003)." (PMID 33299882, 2020). "The messenger RNA of GJA1 gene was identified in tumor cells which was contrary to the characteristics of pseudogenes (inability to produce functional mRNA and proteins)." (PMID 33126609, 2020). "Both the chi-squared test and the logistic regression showed that high-GJA1 expression was significantly correlated with keratinization, hormone use, tumor size, and FIGO stage." (PMID 33299882, 2020). "GJA1 (Cx43) is thought to be the most highly expressed connexin in lung tissue and tumours yet it is highly methylated." (PMID 30845770, 2019). "Runx1 is able to promote RSPO3 gene expression and inhibit GJA1 gene expression on tumor epithelial cells, depending on Foxp3 availability." (PMID 26735887, 2016). "It has been suggested that GJA1 is down regulated in different human cancer types, presumably through promoter hyper-methylation, and that it displays tumor suppressor activity." (PMID 23675859, 2013). "The activity of CD8Tex cells directly affects the growth and spread of tumor cells, while the expression of GJA1 and HLA-DQA1 may regulate the strength and direction of immune response." (PMID 38684858, 2024). "While full-length Cx43 has been widely studied as a tumor suppressor and, paradoxically, as a pro-metastatic agent in certain contexts, GJA1-20k may hold distinct regulatory functions." (PMID 39765713, 2024). "Conversely, the expression of SLC16A1 and SLC16A7 genes —encoding MCT1 and MCT2 lactate transporters, respectively—as well as of GJA1 (data not shown) encoding connexin 43 and responsible of lactate diffusion, does not differ between the two tumour subtypes." (PMID 37198319, 2023). "GJA1 gene expression levels were higher in the T2 cell line than A3 and A5 cell lines indicating the possible effect of estrogen and other factors from the tumor environment." (PMID 36293530, 2022). "Combined with scRNA-seq results, we hypothesized that exosomal miR-30b-5p/GJA1 pathway might participate in tumor angiogenesis under hypoxic condition in PDAC through regulating gap junction communication." (PMID 35173549, 2022). "Together, these results suggested that the roles of GJA1 were tumor-type and cell type-dependent, and could partly explain the discrepancy in previous reports that GJA1 had contrasting effects on tumor progression." (PMID 34693020, 2021). "The tumor tissues displayed an enriched expression of transcription factors (e.g., Dlx2, Gbx2, Foxb1, and Nkx2.2) critical for brain development, tanycyte markers (e.g., Ptprz1, Fabp7, Crym, and Gja1), and differentiation markers (e.g., Dcx, Olig1, and Cspg5)." (PMID 33863883, 2021). "GJA1 has two opposite effects on cancers as it can act as an oncogene or a tumor suppressor gene." (PMID 33299882, 2020).
tumor (continued). "GJA1 could facilitate the transmission of cAMP, leading to increased p27 levels and reduced tumor growth by gap junctional intercellular communication." (PMID 33299882, 2020). "The results showed that tumor size (HR, 6.181; 95% CI, 1.219-31.334; p = 0.028), lymphovascular invasion (HR, 5.910; 95% CI, 1.124-31.059; p = 0.036), and the high-GJA1 expression (HR, 4.084; 95% CI, 1.354-12.320; p = 0.013) were the important independent predictors of poor overall survival of CC." (PMID 33299882, 2020). "Importantly, multivariate analysis showed that tumor size, lymphovascular invasion, and the high-GJA1 expression were the important independent predictors of poor overall survival of CC." (PMID 33299882, 2020). "When we compared GJA1 mRNA expression after stratifying patient samples by their intrinsic subtype (Pam50 by genefu), the increase in variance in gene expression of tumor samples relative to normal tissue was observed in every subtype." (PMID 29495625, 2018). "Moreover, DN/Runx1-transfected tumor cells showed a significant upregulation of GJA1 in this cell line demonstrating an inhibitory role of Runx1 on GJA1 promoter." (PMID 26735887, 2016). "Since the pharmacological effect of DOX is manifested through the induction of oxidative stress, we speculate that the observed GJA1 overexpression in DOX-resistant tumor cells may be an attempt by cells to reduce reactive oxygen species production in response to xenobiotic stress." (PMID 41153808, 2025). "The results demonstrated that the relative expression of GJA1 was 7.3553 (6.6179, 8.002) in the age ≤ 60 group and 7.0655 (6.2779, 7.7754) in the age > 60 group with p value ≤ 0.05, and the expression of GJA1 decreased with increasing tumor pathologic and histologic stage." (PMID 38792963, 2024). "Additionally, when comparing the GJA1 expression in TCGA tumors with their corresponding paracancerous tissues as controls, significant upregulation was observed in four tumor types: CHOL, HNSC, KIRC, and LICH, while downregulation was observed in KICH, LUAD, PRAD, and THCA." (PMID 38792963, 2024). "We found that high GJA1 expression was positively correlated with the hallmark gene sets EPITHELIAL_MESENCHYMAL_TRANSITION and TGF_BETA_SIGNALING as well as several other gene sets that were closely associated with tumor progression (data not shown)." (PMID 34693020, 2021). "However, as enhanced gap junction formation may be associated with increased HSC activation, these observations once again demonstrate the tumor-type and cell type-dependent roles of GJA1." (PMID 34693020, 2021). "It was found that high expression of ZYX, GJA1, and TUBA4A indeed correlated well with low sensitivity of tumor cells to DOX and, moreover, to another anticancer drugs, such as vincristine, topotecan, panobinostat, and cytarabine." (PMID 41153808, 2025). "We further investigated the relationship between GJA1 and CD68 expression levels within the tumour microenvironment, with CD68 being a well‐established marker for macrophages." (PMID 39592436, 2024). "Most importantly, we illustrated that LEF1-AS1 played as a competitive endogenous RNA (ceRNA) via sponging miR-221-5p and thereby positively regulated gap junction protein alpha 1 (GJA1) expression, thus aggravated tumor progression and EMT." (PMID 35371339, 2022). "The population of tumor-derived astrocytes was identified by the upregulation of canonical astrocytic markers, including GFAP, AQP4, GJA1, and S100B." (PMID 35803925, 2022). "Five of these signaling proteins (CDKN1B, CDKN1C, PTN, GJA1, and MORF4L2) can act as tumor suppressors." (PMID 32168333, 2020). "Regarding the well-known Cx43 positive effect on cellular adhesion, GJA1-20k could also impact heterocellular adhesion between tumor and bone cells, leading to optimized bone homing of disseminated cells." (PMID 39936974, 2025).
tumor (continued). "Moreover, GJA1 showed a significant relationship with OS, DSS, and PFI in KIRC, indicating that patients with tumor expressing higher levels of GJA1 had a favorable prognosis." (PMID 38792963, 2024). "Furthermore, in TCGA tumors with paracancerous tissue as controls, upregulation of GJA1 expression was found in four tumor types, including CHOL, HNSC, KIRC, and LICH, and downregulation of GJA1 expression was found in KICH, LUAD, PRAD, and THCA." (PMID 38792963, 2024). "Moreover, TIDE database was used to reveal the correlation between GJA1 and CTL dysfunction, which promotes adaptive immune resistance, leading to tumour immune escape." (PMID 39592436, 2024). "Furthermore, a survival analysis was conducted on the individual genes comprising the UBE2C+ tumour cell score, and it revealed statistically significant results for ITPRIP, GJA1, RUNX1T1, CD82, PAPSS2 and ANXA5." (PMID 38894657, 2024). "Together with the tumor-suppressing proteins such as CALR, ENO1, HSP, MSN, and UBC, which were enriched in tumor-suppressive CM, six recombinant proteins, such as HISTONE H4, PPIB, GJA1, CPE, S100A11, and PCOLCE, were identified as extracellular tumor-suppressing proteins." (PMID 36943734, 2023). "TCGA-A tumours showed higher expression of most group I/FTEC epithelial proteins such as KRT7, MSLN, CDH6, ASS1 and EPCAM, while TCGA-B tumours had higher expression of the group III/IOSE mesenchymal proteins ITGA5, HMOX1, SMTN and GJA1 (refs 7, 34)." (PMID 27561551, 2016). "Cx43+/− animals had a lower cell-to-cell communication capacity and elevated proliferation of APTIIs, and the transfection of Gja1 (Cx43 gene) gene in E9 APTII neoplasia cells, in other study, reestablished and rendered these cells to a nonneoplastic state." (PMID 24199196, 2013). "The aim of this study was to investigate the expression of Phf5a and its effect on Gja1 expression in tumor and non-malignant cell lines derived from the BDII rat model with different genetic backgrounds." (PMID 23675859, 2013). "In the rat tumor set, comparison of the gene expression of Phf5a and Gja1 between the EAC and NME samples showed a slight, but not significant, decrease in in expression of Phf5a in the EAC cell lines." (PMID 23675859, 2013). "Next, we explored potential modes of action by investigating several hallmarks of cancer, namely, tumor-promoting inflammation (e.g., increased macrophages, PMNs, epithelial cells, KC, COX2) and proliferative responses (e.g., Ereg), as well as evasion of growth suppression (e.g., Gja1)." (PMID 39771097, 2024). "Second, we did not confirm the in vivo tumor-promoting activity of GJA1 using metastatic xenograft models since the cell lines we used failed to derive lung metastasis, maybe due to the short observation period." (PMID 34693020, 2021). "In addition, GJA1 does not vary directly with ESR1 and HER2 mRNA and protein levels but shows a stronger correlation with PGR mRNA and PR protein in tumor samples." (PMID 29495625, 2018).